STAT3 (signal transducer and activator of transcription 3)
Diseases named in the same sentence as STAT3 in open-access papers (continued):
Sharing a sentence is not in itself a finding about the gene and the disease.
esophageal squamous cell carcinoma (113 papers, 2012 to 2026). Esophageal squamous cell carcinoma (ESCC) is a type of esophageal carcinoma (EC) that can affect any part of the esophagus, but is usually located in the upper or middle third. "In TNBC and esophageal squamous cell carcinoma, for instance, STAT3 activation has been correlated with resistance to chemotherapy agents mediated by STAT3’s regulation of anti-apoptotic proteins such as Bcl-2 and Bcl-xL." (PMID 40075607, 2025). "In summary, in this study, we demonstrate that fedratinib suppresses proliferation, migration, and apoptosis resistance in esophageal squamous cell carcinoma through inhibition of the JAK2/STAT3 signaling pathway." (PMID 41476794, 2025). "Metformin was shown to induce autophagy through the inactivation of the STAT3 and mTOR pathways in esophageal squamous cell carcinoma." (PMID 40176890, 2025). "Another study reported that circ_0006168 modified by N6-methyladenosine promoted EMT in esophageal squamous cell carcinoma through miR-384/STAT3/Snail axis." (PMID 40584619, 2025). "For example, esophageal squamous cell carcinoma (ESCC)‐associated fibroblasts activate signal transducing activator of transcription 3 (STAT3) signaling by paracrine exosomal miR‐21 to induce monocytes to transform into M‐MDSCs, thereby promoting cisplatin resistance." (PMID 38585234, 2024). "Meanwhile, activated-STAT3 also can regulate MMP2 gene transcription via binding to MMP2 promoter in esophageal squamous cell carcinoma (ESCC), leading to ESCC metastasis." (PMID 38560562, 2024). "High expression levels of STAT3 and VEGF are also associated with lymph node involvement in esophageal squamous cell cancer, indicating that STAT3/VEGF pathway promotes cancer cell lymphatic metastasis and is correlated with pTNM stage." (PMID 35356799, 2022). "Exosomal ZFAS1 has also been declared to regulate the proliferation, invasion, migration, and apoptosis of esophageal squamous cell carcinoma by regulating the miRNA-124/STAT3 axis." (PMID 35090549, 2022). "Research suggests that the JAK2/STAT3 pathway is involved in B7-H4-mediated IL-6 secretion in esophageal squamous cell carcinoma (ESCC) cells and enhances the growth and tumorigenicity of cells." (PMID 35505420, 2022). "Hsa-miR-296-5p negatively regulates STAT3 signaling and can function as a tumor suppressor to depress cell metastasis of esophageal squamous cell carcinoma." (PMID 35590240, 2022). "Recent research in esophageal squamous cell carcinoma demonstrated that CAF-derived exosome-packed microRNA-21 via activating STAT3 signaling promoted the generation of monocyte-MDSCs, thereby causing resistance to cisplatin." (PMID 36032075, 2022). "The Janus kinase (JAK)-mediated STAT3 tyrosine phosphorylation signaling cascade is an important pathway triggered by IL-8, as previously reported in esophageal squamous cell carcinoma and prostate tumor." (PMID 36361568, 2022). "Our group demonstrated that blocking the transcriptional activity of STAT3α by STAT3 isoform STAT3β sensitized esophageal squamous cell carcinoma (ESCC) cells to chemotherapeutic agents, namely, cisplatin and 5-FU both in vitro and in vivo." (PMID 32872659, 2020). "And in esophageal squamous cell carcinoma, let-7 regulates IL-6/STAT3 pathway and is a significant determinant of response to chemotherapy." (PMID 32248842, 2020). "The purpose of the present study was to investigate the clinical and prognostic significance of STAT3/p-STAT3 expression in esophageal squamous cell cancer (ESCC) patients." (PMID 32194797, 2020). "Recent research reported that tumor cell-secreted IL-6 and IL-8 impair the activity and function of NK cells via STAT3 signaling, and contribute to esophageal squamous cell carcinoma malignancy." (PMID 32973887, 2020). "Previous research indicated that LINC01535 promoted the proliferation and inhibited the apoptosis of esophageal squamous cell cancer by regulating the JAK/STAT3 signaling pathway." (PMID 33123295, 2020).
esophageal squamous cell carcinoma (continued). "STAT3 is also a target of GSK3β and GSK3β inhibition reduced STAT3 phosphorylation while higher GSK3β expression promoted esophageal squamous cell carcinoma progression through STAT3 in vitro and in vivo." (PMID 31696055, 2019). "But the interesting thing is that our former study showed a G2/M arrest with cyclin B1 down-regulation when the STAT3 was knockdown in TE1 cell line which is also an esophageal squamous cell carcinoma." (PMID 29636641, 2018). "We found in the present study that STAT3 is constitutively activated in a subgroup of esophageal squamous cell carcinoma cell lines and primary tumors." (PMID 29179470, 2017). "The close association between inflammation and esophageal cancers prompted us to examine the expression of STAT3 and its activation in primary esophageal squamous cell carcinomas." (PMID 29179470, 2017). "Inhibition of STAT3 also suppressed the growth and colony formation, and induced apoptosis in the esophageal squamous cell carcinoma cells containing constitutively activated STAT3." (PMID 29179470, 2017). "And the upregulated expression of tumor suppressor let-7a is an extremely important determining factor in reacting to chemotherapy by regulating IL-6/STAT3 pathway in esophageal squamous cell carcinoma." (PMID 29156742, 2017). "Consistent with that idea, B7-H4 facilitates cell proliferation by promoting a positive IL-6/STAT3 loopback pathway in esophageal squamous cell carcinoma." (PMID 27438152, 2016). "Since ZFAS1 has already been studied in esophageal cancer, such as exosomal ZFAS1 promoting proliferation, migration, and invasion of esophageal squamous cell carcinoma by upregulating STAT3 and downregulating miR-124 while inhibiting apoptosis, we chose ZC3H18 for further investigation." (PMID 40070828, 2025). "High expression levels of activated Stat3 (p-Stat3) and VEGF are also associated with lymph node involvement in esophageal squamous cell carcinoma (ESCC), indicating that Stat3/VEGF pathway promotes cancer cell lymphatic metastasis and is correlated with tumor-node-metastasis (TNM) stage." (PMID 37369946, 2023). "However, metformin has also been found to promote autophagy and apoptosis in esophageal squamous cell carcinoma by the downregulation of Stat3 signaling." (PMID 35052471, 2022). "In esophageal squamous cell carcinoma, IL-6 derived from cancer-associated fibroblasts plays the most important role in chemoresistance by upregulating the expression of C-X-C motif chemokine receptor 7 (CXCR7) via the STAT3/nuclear factor-κB (NF-kB) pathway." (PMID 33868231, 2021). "In addition, treatment of esophageal squamous cell carcinoma with metformin was shown to downregulate Bcl-2 expression through STAT3 inactivation in a previous study." (PMID 33652909, 2021). "Importantly, AH057 did not affect the protein levels of NF-κB p65 and pSer365-p65, one of the downstream targets of STAT3 in esophageal squamous cell carcinoma cells." (PMID 32895373, 2020). "Indeed, STAT3 itself is capable of interacting with other STATs; STAT1 for example has been demonstrated to exhibit inhibitory effects against STAT3 signaling in a study on esophageal squamous cell carcinoma." (PMID 31555281, 2019). "Our results are consistent with a recent study of esophageal squamous cell carcinoma (SCC) where IL-6 induced the accumulation of CD11b+CD14+HLA-DR− MDSC by stimulating STAT3 signal and its level in plasma samples was correlated with tumor progression and poor prognosis." (PMID 29100353, 2017). "It remains unclear how variations in p-STAT3 expression influence clinical outcomes in esophageal squamous cell carcinoma (ESCC)." (PMID 26553224, 2015). "Our data support the emerging notion that IL-6 and p-STAT3 are clinically significant predictors, and suggest that IL-6 may represent a suitable target for esophageal SCC treatment." (PMID 23561329, 2013).
esophageal squamous cell carcinoma (continued). "STAT3 expression was upregulated by the Wnt3a, Wnt5a and Wnt6 ligands in cultured mouse embryonic stem cells, and by constitutively activate β-catenin in esophageal squamous cell carcinoma." (PMID 23056515, 2012). "A previous study found that acylglycerol kinase overexpression augmented JAK2/STAT3 sustained activation, promoting tumorigenicity of esophageal squamous cell carcinoma (ESCC)." (PMID 38182570, 2024). "The activation of STAT3 by stimulation of IL-6 and IL-8 secreted from esophageal squamous cell carcinoma (ESCC) cells downregulates the activating receptors (NKp30 and NKG2D) on the surface of NK cells." (PMID 37501379, 2023). "Furthermore, in vivo studies indicated that STAT3 inactivation by the intravenous injection of ultrasound microbubble vesicles carrying the STAT3 ODN-decoy treated with ultrasound irradiation was the most effective in inhibiting esophageal squamous cell carcinoma growth." (PMID 38067351, 2023). "ZFAS1 has been shown to promote the proliferation, migration, and invasion of esophageal squamous cell carcinoma (ESCC) cells, and to inhibit their apoptosis by upregulating STAT3 and downregulating miR-124." (PMID 36545127, 2022). "In mouse esophageal squamous cell carcinoma, CAFs-secreted Wnt family member (WNT2) has been linked to suppression of the DC-initiated antitumor T-cell response via the suppressor of cytokine signaling 3 (SOCS3)/phosphorylated Janus kinase 2 (p-JAK2)/phosphorylated STAT3 (p-STAT3) signaling pathway." (PMID 36338519, 2022). "We and others have previously shown that the STAT3 signaling pathway is activated in some esophageal squamous cell carcinoma (ESCC) cells and is required for the survival and growth of these primary ESCC-derived xenografts." (PMID 30518397, 2018). "For esophageal cancer, constitutively activated STAT3 expression was found in both esophageal squamous cell carcinomas (ESCC) and Barrett’s adenocarcinomas (BAC)." (PMID 25928665, 2015). "Nevertheless, it has been reported that, in esophageal squamous cell carcinoma, miR-125a-5p inhibits the EMT by targeting Stat3 and it resulted in enhanced cytotoxicity of cisplatin." (PMID 40243417, 2025). "In esophageal squamous cell carcinoma, CAFs secrete WNT2 to inhibit the SOCS3/p‐JAK2/p‐STAT3 pathway, thereby suppressing CD8+ T‐cell activation." (PMID 41164803, 2025). "It was also revealed that Niclo induction of p21 and G1 arrest of the cell cycle suppressed the STAT3 signaling pathway and inhibited cell proliferation in esophageal adenocarcinoma cells (BE3) and esophageal squamous cell carcinoma cells (CE48T and CE81T)." (PMID 40650414, 2025). "The oncogenic circ 0000654 in esophageal squamous-cell carcinomas (ESCCs) promotes ESCC proliferation by sponging miR-149-5p and activating the IL-6/STAT3 signaling cascade." (PMID 38192436, 2024). "The growth and metastases of esophageal squamous cell carcinoma cells were promoted by CXCL6 in vivo and in vitro through the activation of the STAT3 pathway." (PMID 37491836, 2023). "Similar results were obtained in esophageal squamous cell carcinoma, where CAF-secreted IL-6 and CAF-derived, exosome-packed, miR-21 promote MDSC differentiation via STAT3 signaling." (PMID 36338519, 2022). "Метформин индуцирует апоптоз и аутофагию в клетках ESCC (Esophageal squamous cell carcinoma) путем инактивации STAT3 и сдерживания экспрессии Bcl-2, а также индуцирует апоптотические пути в клетках рака надпочечников и поджелудочной железы путем активации каспазы-3." (PMID 36337018, 2022). "IL-6 secretion by esophageal squamous cell carcinoma (ESCC) CAFs, furthermore, increases upon coculture with tumor cells, activating STAT3/NF-κB signaling leading to an induction in CXCR7 expression enhancing chemoresistance to cisplatin." (PMID 35267539, 2022). "In esophageal squamous cell carcinoma, TOPK was positively correlated with tumor metastasis by activating Src/GSK3β/STAT3 signaling pathway." (PMID 33842463, 2021).
esophageal squamous cell carcinoma (continued). "In esophageal squamous cell carcinoma (ESCC), IL-6 released by CAFs increased the chemoresistance of ESCC to cisplatin by increasing the chemokine receptor CXCR7 expression in tumor cells through the STAT3/NF-κB axis." (PMID 35814444, 2022). "Moreover, STAT3 was shown to induce the expression of hypoxia-inducible factor (HIF)-1, a transcription factor which is induced during hypoxia, in esophageal squamous cell carcinoma (ESCC) via binding to its promoter." (PMID 34858425, 2021). "Not surprisingly, SHP2 suppressed the proliferation of esophageal squamous cell cancer by inhibiting STAT3 phosphorylation, and depletion of SHP2 resulted in the attenuation of cisplatin sensitivity." (PMID 34771643, 2021). "The Janus Kinase 2/Signal Transducer and Activator of Transcription 3 (JAK2/STAT3) pathway plays an important role in the occurrence, development and metastasis of esophageal squamous cell carcinoma (ESCC) and is related to the development of resistance to ionizing radiation in ESCC." (PMID 33330321, 2020). "In particular, niclosamide (2.5–10 μM) suppressed the STAT3 signaling pathway in esophageal adenocarcinoma cells (BE3) and esophageal squamous cell carcinoma cells (CE48T and CE81T) by impairing both STAT3 phosphorylation on Y705 residue and STAT3 protein expression." (PMID 32668817, 2020). "Increased H19 expression promoted the epithelial–mesenchymal transition, growth, and invasion of ESCC (esophageal squamous cell carcinoma) and NPC by inhibiting E-cadherin expression and modulating the STAT3/EZH2/β-catenin pathway." (PMID 41020820, 2025). "In esophageal squamous cell carcinoma (ESCC), CAF‐derived WNT2 inhibits DC differentiation through the SOCS3/p‐JAK2/p‐STAT3 signaling cascade, thereby suppressing immune responses." (PMID 41164803, 2025). "In esophageal squamous cell carcinoma (ESCC), B7-H3 enhanced glucose turnover through the phosphorylation of pyruvate kinase M2 (PKM2) and the activation of STAT3 signaling pathways." (PMID 40214484, 2025). "STAT3 inhibitors suppress STAT3 activation, down-regulate HIF-1α expression, and up-regulate the radiosensitivity of esophageal squamous cell carcinoma (ESCC) in vivo and in vitro." (PMID 38778409, 2024). "lncRNA Xist involves esophageal squamous cell carcinoma development via regulation of miR-101/EZH2 axis, and facilitates esophageal squamous cell carcinoma proliferation, apoptosis, migration, and invasion via regulation miR-494/CDK6 axis and activation of JAK2/STAT3 signal pathway." (PMID 34178980, 2021). "In esophageal squamous cell carcinoma (ESCC), AGK directly binds to the Janus kinase homology 2 (JH2) domain of JAK2 to block the inhibition of JAK2 mediated by JH2, which leads to the activation of the JAK2/STAT3 signaling pathway and enhances the tumorigenicity of ESCC cells in vivo and in vitro." (PMID 34368119, 2021). "In esophageal squamous cell carcinoma (ESCC), ZFAS1 can shuttle between tumor cells in the form of exosomes and act as ceRNA to downregulate miR-124, thereby upregulating STAT3 and ultimately inhibiting cellular apoptosis and promoting proliferation, migration, and invasion." (PMID 37178254, 2023). "Furthermore, in esophageal squamous cell carcinoma (ESCC), CAF-derived exosomal miR-21 and IL-6 synergistically promoted the generation of monocytic myeloid-derived suppressor cells (M-MDSCs) via activating STAT3 by IL-6 in an autocrine pathway." (PMID 39684264, 2024). "Consistent with Sugimura K’s study in esophageal squamous cell carcinoma, we here found that let-7b was downregulated in TNBC and had a negative correlation with STAT3 levels." (PMID 32248842, 2020). "Whereas STAT3 is not described as a direct substrate, inhibition of GSK3β after stimulation with IFN-γ, IL-6, or IFN-α reduces the phosphorylation of STAT3 on Y705, and GSK3β modifies STAT3 phosphorylation in esophageal squamous cell carcinoma." (PMID 31862381, 2020).
Stroke (112 papers, 2011 to 2026). Sudden impairment of blood flow to a part of the brain due to occlusion or rupture of an artery to the brain. "Further bioinformatic analysis of our RNA-seq data revealed the upregulation of other genes in the IL6/JAK/STAT3 expression signatures in mouse stroke brains upon the loss of PPARα, as well." (PMID 40362325, 2025). "Genetic evidence linking these factors to vascular disease includes a variant in the RUNX1 locus associated with stroke (rs116262092-A) and colocalization of a STAT3 VSMC eQTL with a CAD GWAS signal." (PMID 39215134, 2024). "To explore the mechanisms by which BACE-1 inhibits the beneficial phenotype of microglia, we noted that STAT3 was closely associated with the microglial polarization shift and microglia-dependent regulation of neuroinflammation and phagocytosis in stroke." (PMID 37552127, 2023). "This inhibited STAT3 phosphorylation, suppressed the release of inflammatory factors, increased neuronal synaptic protein expression, reduced synaptic loss, and promoted neurological function recovery after stroke." (PMID 40919080, 2025). "Therefore, PPARα likely restrains the expression of genes linked to IL6/JAK/STAT3 signaling to prevent rampant neuroinflammation in the subacute stroke phase." (PMID 40362325, 2025). "Besides, EA downregulated the expression of Janus-activated kinase 2 (JAK2)/signal transducer and activator of transcription 3 (STAT3), which was associated with cognitive dysfunction after stroke." (PMID 38379403, 2025). "In particularly, MG 3 cluster was found to show the overexpression of 18 genes involved in JAK–STAT signaling pathway (mmu04630), particularly including STAT3, which contributes to stroke-associated neuroinflammation due to overactivation as validated in previous studies." (PMID 35578342, 2022). "However, the diagnosis of APS in this patient suggested the autoimmune etiology of stroke, which would be consistent with a partial effectiveness of baricitinib in controlling STAT3-GOF-associated immune dysregulation, so that we will consider the reintroduction of a JAKi." (PMID 39247195, 2024). "Since the microglia-mediated pathogenic inflammatory cascade in the brain parenchyma and the phosphorylation extent of STAT3 are major pathogenic drivers contributing to I/R brain injury, the discovery of CP-07 might have potential clinical utility for stroke treatment." (PMID 37408577, 2023). "Our mouse model is that of chronically reduced STAT3, which may render ECs dysfunctional prior to ischemic insult, and may have further physiological relevance since a reduction in brain STAT3 protein levels is observed in aging, a risk factor for stroke." (PMID 36293020, 2022). "Since both the EPO/EpoR and the JAK2/STAT3 pathways have been implicated as molecular targets for ischemic stroke prevention and treatment, the activation of both of these cell pathways and their downstream signaling cascades is recognized as a promising therapeutic approach for stroke patients." (PMID 28848617, 2017). "Another study showed that the downregulation of circulating forkhead box protein P1 (circFOXP1) in stroke accelerated the degradation of the signal transducer and activator of transcription 3 (STAT3) by binding to and enhancing its ubiquitination." (PMID 40943204, 2025). "Stroke-associated microglial clusters showed microglia-specific dysregulation of PANoptosis regulators (MCL1, TNFRSF1A, and STAT3), with TNFRSF1A upregulated in the ischemic core." (PMID 41235394, 2025). "Consistently, catalpol has been found to increase cerebral blood flow and stimulate stroke-induced STAT3 activation, subsequently restoring STAT3 activity by facilitating its binding to VEGF." (PMID 40362263, 2025). "Based on the Western blotting results, it can be concluded that macrophage polarization in the brain following stroke primarily occurs through IL-10-mediated Stat3 signaling pathways." (PMID 40365292, 2025).